FMR1 (fragile X messenger ribonucleoprotein 1)
Diseases named in the same sentence as FMR1 in open-access papers (continued):
Sharing a sentence is not in itself a finding about the gene and the disease.
autism (continued). "Studies from Fmr1 KO mice by in vivo two-photon calcium imaging found that close to half of the neurons in layer 2/3 of S1 lost their adaptation to repetitive whisker stimulation, which may contribute to somatosensory hyper-responsiveness in autism." (PMID 37691105, 2023). "The rates of FMR1 expansion among ASD patients vary widely across studies, depending on different factors including ethnic background, small sample sizes in various studies, possibility of referral bias, diagnostic criteria for autism, and method of FXS diagnosis." (PMID 34926684, 2021). "Fmr1 KO mice show significant repetitive/stereotypic behavior, recapitulating perseverative symptoms in FXS and autism patients." (PMID 32179850, 2020). "Blockade of the enzyme that degrades anandamide, leading to higher levels, also reverses social impairments found in two different autism mouse models, BTBR and fmr1 knockouts." (PMID 31548888, 2019). "Despite the significant differences observed between the two complete and incomplete FMR1 mRNA FM-only groups on ADOS CSS, the overlap between autism features and anxiety, particularly social anxiety, cannot be ignored." (PMID 31073396, 2019). "The study, however, did not dichotomize FXS participants based on the presence of complete or incomplete FMR1 silencing, and did not report on whether this stratification strategy resulted in associations with elevated autism features in FXS, as reported in this study." (PMID 31073396, 2019). "Simultaneous deletion of both FMR1 and AFF2 in males results in severe ID and variable other features including hypotonia, epilepsy, obesity, and autism." (PMID 30264515, 2018). "In the P21 rat’s brain of the formalin group, the expression of autism-related gene neurexin 1 (NRXN1), fragile X mental retardation 1 (FMR1), and oxytocin was significantly downregulated, consistent with the gene alteration in ASD." (PMID 27184741, 2016). "Nevertheless, further work is needed to understand how FMR1 is involved in the pathogenesis of different neurodevelopmental phenotypes, that is, ADHD, autism and schizophrenia, each of which has very different phenotype features and treatments." (PMID 26573769, 2016). "In this study, we examined the effects of memantine on the cultured cerebellar granule cells (CGCs) from Fmr1 knockout (Fmr1-KO) mice, which is a mouse model for FXS and currently also used as a mouse model for autism studies." (PMID 22615862, 2012). "A recent study demonstrated that the daily E/I balance was disrupted in Fmr1 KO and BTBR mice, two other autism mouse models, suggesting that disrupted daily E/I balance may be a common feature of autism-related models." (PMID 41408339, 2025). "In contrast, Fmr1 knockout (KO) mice, a model of autism, find social and non-social interactions equally aversive, especially at close proximity, and their cortical/striatal neurons are less able to discriminate social valence." (PMID 40382316, 2025). "Subsequently, the absence of the FMR1 protein (FMRP) leads to the FXS phenotype and autism." (PMID 39199432, 2024). "Finally, Tau-targeting ASO also effectively alleviated autism-like phenotypes and promoted P38/MAPK signaling in Fmr1 KO mice." (PMID 37936174, 2023). "These include the increased latency of peaks in the ERP of ASD models (though the decreased amplitude of the N1 peak seen in human ASD was not well recapitulated) and increased amplitude of the N1 peak in Fmr1 models, which matches the divergence in FXS from the typical human autism endophenotype." (PMID 36042393, 2022).
autism (continued). "Studies of FMR1 CGG repeats using DNA testing have found widely varying levels of abnormalities in the FMR1 gene, while some studies have found no abnormal FMR1 genes in patients with autism." (PMID 34926684, 2021). "Interestingly, four mouse models of autism, including patDp/+, NLG3 R451C, BTBR, and Fmr1-KO mice, show increased protein turnover at spines as well as increased formation and elimination of spines." (PMID 34579720, 2021). "For example, although Top3β interacts with FMRP, the phenotypes of Top3β-KO mice are not identical to those of the Fmr1 mice (an autism model)." (PMID 32561719, 2020). "In contrast, decreased levels of FMR1 mRNA were associated with decreased intellectual functioning in FXS males (p = 0.029), but not autism features, when combined with the PM/FM mosaic group." (PMID 31073396, 2019). "This study demonstrated that none of the molecular markers analysed, including FMR1 mRNA in blood, were associated with communication-social total scores of the ADOS or with the overall autism rating." (PMID 31073396, 2019). "Molecular changes may also influence the expression of genes involved in autism symptoms and genetic syndromes such as GABRB3, FMR1, TSC1 and TSC2." (PMID 29340132, 2018). "Consistent with the higher seizure susceptibility in autism and FXS patients, Fmr1 KO mice showed audiogenic seizures (AGS), which were absent in WT and Adcy1 KO mice." (PMID 28218269, 2017). "In Fmr1 KO mice, treatment with MPEP or AFQ056 rescues deficits in prepulse inhibition (PPI), a sensorimotor gating behavior that is disrupted in subjects with autism, schizophrenia, and other psychiatric disorders." (PMID 23803181, 2013). "By integrating detailed phenotypic analysis with neuroimaging studies in autism and FXS, future research may provide important insights into the role of FMR1 in social-communicative phenotypes." (PMID 22934085, 2012). "Premutation repeat expansions (55 to 200 CGG repeats) may also give rise to autism spectrum disorders (ASD), including both autism and PDD-NOS, through a different molecular mechanism that involves a direct toxic effect of the expanded CGG repeat FMR1 mRNA." (PMID 20858229, 2010). "Relevant to the effect of MPH in Shank2- and Fmr1-deficient mice, hyperactivity of Trpm1-deficient mice may not be related to ADHD, but instead autism which is also one of the phenotypes of 15q13.3 microdeletion syndrome." (PMID 33785025, 2021). "The study also explored relationships between the levels of FMR1 mRNA (if not completely silenced) in PBMCs and severity of intellectual functioning and autism features using improved methodologies for more accurate quantification of mRNA in FMR1related disorders." (PMID 31073396, 2019). "In mouse models of autism, methylphenidate did not rescue hyperactivity in Fmr1-/- mice." (PMID 30337855, 2018). "Unlike autism, which may involve symptoms related to multiple genes, FXS is caused by silencing one gene (FMR1) that codes for the Fragile X mental retardation protein (FMRP)." (PMID 29593596, 2018). "Consistent with the report that hyperactivity in Fmr1 KO mouse can be rescued by THIP application, the current study showed that THIP changed the excitability of pyramidal cells, suggesting that THIP may be useful as a potential therapeutic agent in autism." (PMID 28966979, 2017). "Interestingly enough, some other mouse models of autism were negative in the three chamber test as Nlgn3 knock-in mouse and Fmr1." (PMID 28448442, 2017). "Altogether, our findings could inform prioritization of studies aimed to identify salient molecular and cellular dysfunctions arising from Fmr1 silencing and potentially contribute to uncovering of shared cellular pathologies between FXS and other disorders in the autism spectrum." (PMID 25849048, 2015).
autism (continued). "The full mutation, in which alleles have >200 CGG repeats, causes transcriptional silence of FMR1 gene, absence of the fragile X mental retardation protein (FMRP) and well characterized features of the fragile X syndrome, which was the most common cause of inherited mental retardation and autism." (PMID 25050920, 2014). "This may also explain the lack of associations observed between FMR1 mRNA levels and autism features in the FM-only male group with incomplete silencing, while group differences on ADOS CSS when stratified based on the presence or absence of FMR1 mRNA were present." (PMID 31073396, 2019). "Here, we find that Adcy1 mRNA translation is aberrantly increased in the absence of FMRP and altered ADCY1 expression contributes to the enhanced ERK1/2 signalling and autism-related behaviours in Fmr1 KO mice." (PMID 28218269, 2017). "Mice lacking the Fmr1 gene model aspects of the pathophysiology and many of the abnormal behaviors seen in FXS and autism, including cognitive impairments, increased spontaneous motor activity (but see 17,18), increased seizure susceptibility; and altered social behaviors." (PMID 24205018, 2013). "In particular, the pallium neuron LTD is augmented in the absence of fmr1, suggesting that exaggerated LTD may be also responsible for aspects of abnormal neuronal responses in FXS, such as autism." (PMID 22779005, 2012). "From these lists, we observed a significant enrichment of autism-related genes (97/738; p < 4.004 10−7) and FMRP targets (185/738, 6.885 10−12) in the list of genes downregulated in FMR1 KO NPCs, but not in the list of genes that were upregulated in FMR1 KO NPCs." (PMID 37834379, 2023).
fragile X-associated tremor/ataxia syndrome (187 papers, 2008 to 2026). Fragile X-associated tremor/ataxia syndrome (FXTAS) is a rare neurodegenerative disorder characterized by adult-onset progressive intention tremor and gait ataxia. "Fragile-X-associated tremor/ataxia syndrome (FXTAS) is a progressive neurodegenerative disorder associated with the FMR1 gene premutation, characterized by the presence of 55 to 200 CGG triplet repeat expansions." (PMID 40141467, 2025). "The FMR1 gene is also involved in Fragile X-associated tremor/ataxia syndrome (FXTAS) and Fragile X-associated primary ovarian insufficiency (FXPOI) carrying 55–200 CGG repeats (fragile X ‘premutation’)." (PMID 39465205, 2024). "CGG repeat expansions in the range of 55–200 within the FMR1 gene cause fragile X-associated tremor/ataxia syndrome (FXTAS)." (PMID 38929088, 2024). "On the other hand, Fragile X-associated tremor/ataxia syndrome (FXTAS) is a distinct disorder caused by the premutation in the FMR1 gene." (PMID 38578387, 2024). "For example, fragile X-associated tremor/ataxia syndrome (FXTAS) is a neurodegenerative disease that affects premutation carriers (55–200 CGG repeats) in the FMR1 gene." (PMID 36814905, 2023). "Fragile X-associated tremor/ataxia syndrome (FXTAS) is an X-linked late-onset degenerative disorder in Fragile X disease premutation carriers of a CGG repeat expansion in FMR1." (PMID 38132285, 2023). "We noted some overlap in clinical features in these diseases and fragile X-associated tremor/ataxia syndrome (FXTAS) caused by CGG repeat expansions in FMR1." (PMID 36670296, 2023). "Neurodegeneration in Fragile X-associated tremor/ataxia syndrome (FXTAS) is caused by a CGG trinucleotide repeat expansion in the 5′ UTR of FMR1." (PMID 37352983, 2023). "Fragile X-associated Tremor/Ataxia Syndrome (FXTAS) is a neurodegenerative disorder associated with the FMR1 premutation." (PMID 37686279, 2023). "Aging FMR1 premutation carriers are at risk of developing neurodegenerative disorders, including fragile X-associated tremor/ataxia syndrome (FXTAS), and there is a need to identify biomarkers that can aid in identification and treatment of these disorders." (PMID 38034068, 2023). "FMR1 RAN translation causes the neurodegenerative disorder Fragile X-associated tremor/ataxia syndrome (FXTAS)." (PMID 36393867, 2022). "Nearly half of men with FMR1 premutation develop a neurodegenerative disorder; Fragile X-Associated Tremor/Ataxia Syndrome (FXTAS)." (PMID 36421873, 2022). "The stability of FMR1 mRNA can be affected in the late adult-onset neurodegenerative disorder fragile X-associated tremor and ataxia syndrome (FXTAS)." (PMID 35641906, 2022). "Fragile X-associated tremor/ataxia syndrome is a disease caused by a CGG trinucleotide repeat amplification in the 5′UTR of the FMR1 gene, which is easily misdiagnosed as NIID." (PMID 36545534, 2022). "Fragile X-associated tremor/ataxia syndrome (FXTAS) is a late-onset neurodegenerative disorder caused by a “premutation” (55–200 CGG repeats) in the FMR1 gene at Xq27.3." (PMID 35207276, 2022). "CGG repeat expansions in the FMR1 5’UTR cause the neurodegenerative disease Fragile X-associated tremor/ataxia syndrome (FXTAS)." (PMID 35904811, 2022). "Smaller expansions of CGG trinucleotide repeats in the FMR1 X-linked gene termed ‘premutation’ lead to a neurodegenerative disorder: Fragile X Associated Tremor/Ataxia Syndrome (FXTAS) in nearly half of aged carrier males, and 8–16% females." (PMID 34116720, 2021). "Fragile X Associated Tremor/Ataxia Syndrome (FXTAS) is a neurodegenerative disorder affecting carriers of premutation alleles (PM) of the X-linked FMR1 gene, which contain CGG repeat expansions of 55–200 range in a non-coding region." (PMID 34880790, 2021). "Fragile X-associated tremor/ataxia syndrome is a late-onset condition that is caused by abnormally high numbers of 55–200 CGG-repeats in the 5'UTR of the FMR1 gene." (PMID 33777106, 2021).
fragile X-associated tremor/ataxia syndrome (continued). "For example, a premutation in the FMR1 gene is associated with Fragile X-associated tremor/ataxia syndrome (FXTAS), which manifests itself as a progressive neurodegenerative disease with pronounced manifestations." (PMID 34362406, 2021). "Fragile X-associated tremor/ataxia syndrome (FXTAS) is a neurodegenerative disorder associated with a premutation cytosine-guanine-guanine (CGG) trinucleotide repeat expansion of the FMR1 gene." (PMID 33374331, 2020). "Individuals with premutation alleles of the FMR1 gene are at risk of developing fragile X-associated tremor/ataxia syndrome (FXTAS), a neurodegenerative condition affecting sensorimotor function." (PMID 31632248, 2019). "Fragile X-associated tremor/ataxia syndrome (FXTAS) is a neurodegenerative disorder associated with a premutation repeat expansion (55–200 CGG repeats) in the 5′ noncoding region of the FMR1 gene." (PMID 31481131, 2019). "Fragile X-associated tremor ataxia syndrome (FXTAS) is caused by a CGG repeat expansion in the FMR1 gene." (PMID 31098852, 2019). "CGG repeat expansions in FMR1 cause the neurodegenerative disorder Fragile X-associated Tremor/Ataxia Syndrome (FXTAS)." (PMID 31665086, 2019). "Overproduction of FMR1 mRNA in FMRP premutation carriers has been linked to emergence of fragile X-associated tremor/ataxia syndrome (FXTAS) which is a progressive disorder associated with cognitive decline intention tremor." (PMID 31174462, 2019). "In our analysis, TCF4 was noticed to activate fragile X mental retardation 1 (FMR1) gene, which is associated with the neurodegenerative condition such as Fragile X-associated tremor ataxia syndrome (FXTAS)." (PMID 31484947, 2019). "Fragile X-associated tremor/ataxia syndrome (FXTAS) is a late-onset neurodegenerative disorder caused by expanded CGG (CGGexp) trinucleotides in the 5′-untranslated region (5′UTR) of the FMR1 gene." (PMID 29971092, 2018). "FMR1 is a member of the fragile X-related gene family and is responsible for developing both fragile X syndrome and Fragile X-associated Tremor/Ataxia Syndrome, an adult onset neurodegenerative disorder." (PMID 30389934, 2018). "Fragile X-associated tremor/ataxia syndrome (FXTAS) is a late-onset neurodegenerative disorder caused by expanded CGG (CGGexp) trinucleotides in the 5′UTR of the FMR1 gene encoding fragile X mental retardation protein (FMRP)." (PMID 29971092, 2018). "Fragile X-associated tremor/ataxia syndrome is a human adult-onset neurodegenerative disorder caused by an expanded trinucleotide repeat in the FMR1 gene." (PMID 27013529, 2016). "For instance, hippocampal neurons with CGG repeat expansions in the FMR1 gene, which give rise to fragile X-associated tremor/ataxia syndrome (FXTAS), accumulate more heterochromatin but in smaller foci." (PMID 27595843, 2016). "RAN translation is also initiated by hexanucleotide GGGGCC repeat expansion in intron 1 of the C9FTD/ALS gene C9ORF72, and by CGG repeat expansion in the 5’ UTR of FMR1, causing fragile X-associated tremor ataxia syndrome (FXTAS)." (PMID 26086378, 2015). "Fragile X-associated tremor/ataxia syndrome (FXTAS) is a late-onset neurodegenerative disease caused by CGG repeat expansion mutations within the 5' untranslated region (UTR) of the FMR1 gene." (PMID 25538551, 2014). "Another disorder associated with the FMR1 gene is Fragile X-associated tremor/ataxia syndrome (FXTAS), a neurodegenerative disorder associated with expansion of multiple CGG repeats (premutations) located within the gene." (PMID 25628535, 2014). "Fragile X associated tremor/ataxia syndrome (FXTAS) is a late onset neurodegenerative disorder caused by aberrant expansion of CGG repeats in 5′ UTR of FMR1 gene." (PMID 23626835, 2013). "CGG expansion in the FMR1 gene of premutation FXS carriers results in progressive neurodegeneration associated with parkinsonism in fragile X-associated tremor/ataxia syndrome (FXTAS)." (PMID 24205018, 2013).